VPS13B-DT (VPS13B divergent transcript)
Synonyms: OLC8
Gene: Long non-coding RNA gene on chromosome 8 (98,956,967 to 99,013,743, reverse strand). Ensembl gene ENSG00000253948.
Diseases named in the same sentence as VPS13B-DT in open-access papers:
VPS13B-DT is named in the same sentence as 3 diseases in open-access papers, as found by Europe PMC text mining. Sharing a sentence is not in itself a finding about the gene and the disease.
VPS13B-DT shares sentences with these, for which no sentence is quoted: cancer (1 paper); gastric cancer (1); tumor (1).